TNF (tumor necrosis factor)
Diseases named in the same sentence as TNF in open-access papers (continued):
Sharing a sentence is not in itself a finding about the gene and the disease.
cancer (continued). "KEGG enrichment showed that genes were particularly enriched in the IL-17 signaling pathway, AGE-RAGE signaling pathway, toll-like receptor signaling pathway, tumor necrosis factor signaling pathway, transcriptional deregulation in cancer, and other pathways." (PMID 33299870, 2020). "TNFα binds TNFR on cancer cells and induces, among other pathways, a signaling cascade that promotes p65 nuclear translocation via IKKβ." (PMID 33324403, 2020). "When CD8+ T cells are activated, such as through the recognition of neoantigens or viral antigens presented by cancer cells, they produce inflammatory cytokines like tumor necrosis factor alpha (TNFα) and interferon gamma (IFNγ)." (PMID 34212113, 2020). "CD4+ T lymphocytes contribute to the fight against cancer by the release of pro-inflammatory cytokines IL-2, TNF-α, and INF-γ, which, in turn, activate T lymphocytes, NK, and macrophage cells, while enhancing antigen presentation." (PMID 33383887, 2020). "From the chart downloaded from UALCAN, we can see that TRAIL and TNF do have high mRNA levels in a few types of cancer." (PMID 32325691, 2020). "We have previously reported that adipose tissue-derived stem cells (ASCs) cultured at high cell density can induce cancer cell death through the expression of type I interferons and tumor necrosis factor (TNF)-related apoptosis-inducing ligands (TRAIL)." (PMID 32485960, 2020). "Since its discovery in 1975, TNFα has been a subject of intense study as it plays significant roles in both immunity and cancer." (PMID 33324405, 2020). "Cachexia is characterized by the activation of systemic inflammation, which is reflected by increased serum levels of C-reactive protein; however, the catabolic drive during cancer cachexia can also be reflected by other cytokines, including IL-6 and TNFα." (PMID 32708527, 2020). "Cell molecules including transcription factors (e.g., NF-κB, STAT3, HIF1α) and cytokines (e.g., IL-6, Cox-2, and TNF-α) coordinate together and lead to the amplification of inflammation and creation of a suitable environment for cancer growth." (PMID 32758196, 2020). "Altogether, these results suggest that TAT-FADD has the potential to target constitutive NF-κB signaling and abrogates TNF-α-mediated pro-survival NF-κB signaling in cancer cells." (PMID 32961826, 2020). "KEGG enrichment indicated several pathways regulated by brazilin such as the TNF signaling pathway, cellular senescence, and pathways in cancer." (PMID 32986377, 2020). "Leptin, IL-6, and TNF-α are proinflammatory cytokines produced by adipose tissue and that are also increased in cancer, while adiponectin protects against tumorigenesis and its serum levels are usually decreased in cancer patients." (PMID 32604970, 2020). "A different approach that has attracted a great of attention is the use of TNF-α inhibitors, such as Etanercept, as candidates for cancer biotherapy." (PMID 32883235, 2020). "Research emphasizes the critical role of humoral factors secreted by cancer cells in the patient’s tissues in the regulation of processes leading to cachexia, which also include pro-inflammatory cytokines IL-6, TNF-α, IFNγ, IL-1α, and IL-1β." (PMID 33158194, 2020). "SH3 domain-binding glutamic acid-rich-like protein 3 (Sh3bgrl3) protein is implicated in cell redox homeostasis and is known to be upregulated in some cancers, and potentially involved in cell resistance to TNF-α induced apoptosis." (PMID 32973493, 2020). "Conversely, cancer cells treated with TNF-α and trastuzumab had a similar decrease in viability as trastuzumab-treated cancer cells co-cultured with T-cells (p = 0.32)." (PMID 33292267, 2020). "Studies have demonstrated that telomerase can directly regulate recruitment to promoters of NF-κB target genes, such as those encoding interleukin-6 (IL-6) and tumor necrosis factor alpha (TNF‐α) that are critical for inflammation and cancer progression." (PMID 33329574, 2020).
cancer (continued). "The nuclear factor kappa B (NF-κB) signaling pathway and its downstream inflammatory factors interleukin-6 (IL-6), interleukin-1β (IL-1β), and tumor necrosis factor-α (TNF-α) play an important regulatory role in the developmental process of cancer pain." (PMID 32431607, 2020). "Previous studies have shown that phosphorylation and degradation of the IκBα protein promotes the activation of NF-κB and the expression of TNF-α, IL-1β, and IL-6, participating in the formation and development of cancer pain." (PMID 32431607, 2020). "Cytokines are important mediators in the development of cancer, for example, TNF-α promotes cancer cachexia by affecting the storage of TG." (PMID 32584390, 2020). "Other cytokines related to cancer-mediated inflammatory process such as IL-8, TNF-α and CRP were also reduced by exercise training (18 m/min for 12 weeks, at 30 min for 5 days per week) in breast cancer mice." (PMID 33371214, 2020). "It has long been recognized that doxorubicin increases the therapeutic potential of IL-12, TNF-α, and IL-2 in animal models of cancer." (PMID 32340275, 2020). "This study showed that TNF-α shows a synergistic effect with AIMs, and it can be used as a therapeutic tool by inhibiting NF-κB activity in platinum drug resistant cancers." (PMID 32784919, 2020). "Our assays also demonstrated fundamental differences in NF-κB signalling dynamics compared to cancer cell lines, with TNF-induced p65 oscillations being heavily damped in organoids." (PMID 32958515, 2020). "Accordingly, upon TM-mediated cancer cell lysis, UniCAR T-cells secreted the cytokines TNF-α, IFN-γ, GM-CSF and IL-2." (PMID 32370811, 2020). "While RIPK1, which acts in concert with RIPK3 to form fibrils and phosphorylate MLKL, is consistently preserved in cancers because it is also required for the operation of the TNF/TNFR1/NF-κB signaling axis." (PMID 32393742, 2020). "Interleukin-1 beta (IL-1β), IL-6, IL-10, transforming growth factor beta (TGF-β), and tumor necrosis factor alpha (TNF-α) are representative cytokines that are important modulators of inflammation and cancer progression." (PMID 33322487, 2020). "Asynchronous simulation model was used to predict cell fate; i.e. survival, proliferation and apoptosis when TNF-α pathway was active in cancer cells alone versus the condition where macrophages were considered." (PMID 32883235, 2020). "With respect to the role of TNFα and its signaling pathways in regulating the immune system in cancer, it has been reported that the TNFR2-mediated signaling has a critical role not only in the survival but also in the activity of the MDSCs." (PMID 32391269, 2020). "Based on previous findings about higher cytotoxic effects of TNF-α on some MDR cancer cells compared to sensitive cancer cells, introducing TNF-α as new member of agents with CS ability is plausible." (PMID 32742605, 2020). "Functional variants ‐173 G > C (rs755622) and ‐794CATT5‐8 (rs5844572) MIF gene have been associated with the risk in several types of cancer, as well as with the increase of soluble levels of MIF and TNFα." (PMID 31978276, 2020). "Growth factors and inflammatory cytokines such as PDGF, TGF-β, TNF-α, IL-6, and IL-1β, expressed by cancer cells during HCC, activate and transform quiescent fibroblasts into myofibroblasts and then into CAFs." (PMID 32984031, 2020). "Overexpression of miR-203 and miR-200c suppressed cancer stemness in TNFα-treated HPV16-immortalized cells." (PMID 31911577, 2020). "The genes that were changed at 120 min were mostly related to the TNF signaling pathway, microRNAs in cancer, and MAPK signaling pathway." (PMID 32508763, 2020).
cancer (continued). "TNF-α is a versatile cytokine that plays diverse roles in cancer through the engagement of two membrane receptors named p55/TNFR1 and p75/TNFR2." (PMID 33202705, 2020). "We find that the regulation of CASP9 through NF-κB-mediated FFL plays a pro-apoptotic role in the TNFα-promoted apoptosis of cancer cells induced by DOX." (PMID 32225068, 2020). "The paradoxical role of TNF-α and its receptors either as promoters or inhibitors of cancer progression has been widely studied." (PMID 33202705, 2020). "We found that depletion of MLKL enhances TRAIL and TNFα-induced apoptosis in various cancer cell lines and with the enhancement of cell death being RIP3-independent." (PMID 32917855, 2020). "Thus, TNF and anti-TNF therapies may both have carcinogenic benefits and risks in different cancer types and the causal role of the cytokine in the development of a wide range of site-specific cancers warrants further evaluation." (PMID 32805626, 2020). "The presence of T-cells significantly increased TNF-α expression in trastuzumab-treated cancer cells (p = 0.02)." (PMID 33292267, 2020). "TAMs produce multiple growth factors and inflammatory cytokines (IL–1β, IL–6 and TNF–α), each associated with EMT in cancer cells." (PMID 32443890, 2020). "ADAMs anchor through membrane and mediate the shedding and maturity of various membrane proteins such as HB-EGF, TNFα, notch, and cadherins and play roles in neuronal development, neurodegenerative disorders, and cancer progression." (PMID 33204367, 2020). "SM compounds that antagonise cIAP1/2 have received attention as potential cancer therapeutics because cIAP1/2 are overexpressed in many cancer types and their elimination from cancer cells often induces TNF‐driven apoptosis." (PMID 32419365, 2020). "Most of the genes in the subnetworks were inflammatory cytokines and participated in TNF signaling pathways and pathways in cancer, such as Ccl2, Ccl20, Csf1, Cx3cl1, Cxcl1, Cxcl3, Il6, Birc3, Map3k8, Nos2, Nfkb2, Tnfrsf1b, and Vcam1." (PMID 33042984, 2020). "Biglycan promotes EMT in cancer cells, and its expression involves TGFβ/Snail and TNFα/NFkB signals." (PMID 32821344, 2020). "A later study indicated that SMs can affect 48% of cell lines when combined with TNFα, which was found to be ineffective in induction of apoptosis of 51 different cancer cell lines." (PMID 32325691, 2020). "SMs induce cancer cell death predominantly through a cIAP-dependent mechanism regulated by death receptor ligands, such as tumor necrosis factor alpha (TNFα)." (PMID 32325691, 2020). "In other words, many cancer cell lines are resistant to SM-mediated apoptosis with high expression of TNFα." (PMID 32325691, 2020). "Drugs that inhibit TNF-α signaling in inflammatory conditions are therefore of great interest for the treatment of various cancers." (PMID 32486470, 2020). "Through a cell-based screening for miRNAs regulating apoptosis, we found that miR-381-3p negatively regulates TNF-induced apoptosis in multiple human cancer cell lines." (PMID 32411707, 2020). "Intriguingly, several reports indicate that among stimulated pro-inflammatory cytokines, members of the Tumor Necrosis Factor (TNF) family are major players that participate in cancer progression." (PMID 32244288, 2020). "COP9 signalosome 5 (CSN5) was required for TNFα-mediated PD-L1 stabilization in cancer cells, by inhibiting the ubiquitination and degradation of PD-L1." (PMID 32992658, 2020). "In summary, the IKKβ/NF-κB signaling pathway and the pro-inflammatory cytokines TNF-α, IL-1β, and IL-6 play important regulatory roles in the development of cancer pain." (PMID 32431607, 2020). "TNF or TNFR1 blockade synergizes with anti-PD-1 on anti-cancer immune responses against solid tumors in mice." (PMID 33381115, 2020).
cancer (continued). "This duality of RIPK1 function, life or death fates depending on RIPK1’s ubiquitination status mediated by the cIAPs, is what allows SMs to toggle so efficiently between these TNFα-mediated outcomes on cancer cells." (PMID 32393742, 2020). "Pro-inflammatory cytokines such as TNFα, IL-6, and IL-8, which are frequently elevated in cancer patient serum samples, are also involved in both platelet activation and autophagy." (PMID 33365273, 2020). "We are convinced that, blocking the TNF/TNFR2 signaling pathway is truly one stone three birds in cancer microenvironment." (PMID 32546175, 2020). "It suggested that the CCL21 secreted by TNF-α-treated HLEC is involved in the process of cancer metastasis." (PMID 33158173, 2020). "For instance, NK stimulatory receptors like NKG2D can cause the release of perforin and granzyme as well as the induction of apoptosis in cancer cells via the release of TNFα and activation of the FAS ligand (FASL)." (PMID 32752264, 2020). "Lymphocytes also block the proliferation and migration of cancer cells by secreting cytokines, such as interferon-γ and TNF-α." (PMID 32676164, 2020). "Although there is evidence indicating that the apoptosis induced by TNF-α is caspase independent, many other studies reported caspase-3-dependent apoptotic cell death in human cancer or normal cells after exposure to TNF-α." (PMID 32455774, 2020). "TNF-α can induce cancer cell death when treated in high concentration, but in low concentration, it promotes metastasis." (PMID 32455624, 2020). "This combination therapy also up-regulated the level of IFN-γ and TNF-α, which confirmed the efficacy of cancer immunotherapy." (PMID 32408880, 2020). "Another of these pro-inflammatory cytokines is tumor necrosis factor-alpha (TNF-α), which enhances tissue proliferation and cancer metastasis." (PMID 33126555, 2020). "As a test for the diseases, we measured the saliva levels of Abeta42 for AD, CRP for heart disease, and TNF for cancer." (PMID 32019214, 2020). "Trastuzumab treated cancer cells co-cultured with T-cells had increased TNF-α expression compared to trastuzumab treated cancer cells without T-cells (p = 0.02)." (PMID 33292267, 2020). "Here we show the ability of takinib to not only induce TAK1 mediated apoptosis in TNF sensitive cancer cells, but to reduce pro-inflammatory and pro-angiogenic signaling in surrounding TAMs." (PMID 32523651, 2020). "The most studied cytokines in cancer are: tumor necrosis factor (TNF-α), involved in angiogenesis and invasion; Interleukin-1 (IL-1), associated with metastasis, and IL-8-associated proliferation and migration." (PMID 32499779, 2020). "Categories with the highest numbers of annotated proteins included TNF-mediated signaling, cell proliferation, negative regulation of apoptosis, cell migration and angiogenesis, reflecting the cancer-promoting effect of CM ectosomes." (PMID 32331267, 2020). "As a constituent of topical anti-obese creams lipases are used in manufacturing of hair waving and also used for the curing of malignant tumors as digestive aids because lipases are initiate as activators of tumor necrosis factor (TNF)." (PMID 32847584, 2020). "C-reactive protein, tumor necrosis factor, and interleukin-1 are involved in the pathogenesis of cancer, and can decrease serum albumin concentrations." (PMID 33215031, 2020). "IL-1 is an inflammatory cytokine which actions overlap with TNF-α, and can be elevated during cancer cachexia." (PMID 33329046, 2020). "The cancer-specific apoptotic potential of tumor necrosis factor (TNF)-related apoptosis-inducing ligand (TRAIL) has attracted great attention among biologists and oncologists, with some studies using recombinant human TRAIL (rhTRAIL) reaching clinical trials." (PMID 33396409, 2020). "Studies have shown the detrimental role of inflammatory cytokines, TNF-α and IL-6, in the promotion of cancer progression." (PMID 32796516, 2020).
cancer (continued). "Other proinflammatory cytokines, such as TNFα and IFNγ, seem to have an ambiguous effect on cancer progression." (PMID 32733461, 2020). "Our study offers a theoretical basis for the clinical treatment of cancer by inhibiting TNFα and provides a new strategy for overcoming clinical resistance to bevacizumab." (PMID 33214550, 2020). "For osteolytic metastasis, the cancer cells release some cytokines that promotes the activation and maturation of osteoclasts, such as tumor necrosis factor α (TNF-α), macrophage colony-stimulating factor (M-CSF), interleukin 8 (IL8), IL11, etc.." (PMID 33614495, 2020). "PLGA-R837/Cat-based RT plus anti-CTLA4 induced effective long-term immune memory protection against cancer recurrence, sustaining high level of TNF-α and IFN-γ." (PMID 32408880, 2020). "Suppressed NF-κB activation is correlated with sustained c-Jun N-terminal kinase (JNK) activation followed by tumor necrosis factor α (TNF-α)-mediated cell death of cancer cells." (PMID 32823992, 2020). "The results of the KEGG pathway enrichment analysis showed that the top 10 pathways included cancer pathway, TNF signaling pathway, MAPK signaling pathway, P13K-AKT signaling pathway and FoxO signaling pathway." (PMID 33643040, 2020). "In a mouse cancer model, it was shown that endogenous TNF requires TNFR2 to generate thermal hyperalgesia." (PMID 32528961, 2020). "The first network showed hubs around TNF and MMP3 and was associated with cancer, cellular movement, and connective tissue disorders." (PMID 33059716, 2020). "The miRNA–mRNA pairs that were changed at 120 min were mostly related to pathways in cancer, the TNF signaling pathway, HTLV-I infection, and the MAPK signaling pathway." (PMID 32508763, 2020). "Increased production of TNF-α can also lead to activation of the cell survival mechanism of cancer cells, as it undergoes two sequential complexes." (PMID 33187351, 2020). "Lymphotoxin-α (LTA) is the predominant member of the tumor necrosis factor (TNF) ligand family, which responds to immune and inflammatory reaction and plays an important role in the pathogenesis of cancer." (PMID 32420584, 2020). "In particular, TNF-α has been documented to participate in the instigation as well as advancement of cancer." (PMID 32194791, 2020). "TNFα, type I IFN and their related pathways are linked to anti-cancer therapeutic responses and we herein establish that their direct effects on cancer cells are instrumental in addition to their modulation of cancer immune-surveillance." (PMID 31937780, 2020). "Inflammatory diseases and cancer have been documented to possess an excess of pro‐inflammatory molecules such as IL‐1β, TNF‐α, NO and ROS." (PMID 31680470, 2020). "After traversing BBB, cancer cells secrete various cytokines, chemokines, and mediators, particularly IL-1β, TNF-α, IFN-γ, CCL2, CXCL8, and COX2." (PMID 31900168, 2020). "TNF-α increased CDDP sensitivity of both the cancer cells, but there was a difference in intensity; an additive effect and synergistic effect were observed between CDDP and TNF-α in MCF-7 cells and MDA-MB-231 cells, respectively." (PMID 32784919, 2020). "Neutrophils play crucial roles in the pathogenesis of cancer by enhancing the proliferation, invasion, and metastasis of cancer cells via the release of cytokines and chemokines such as interleukin (IL)-6 and tumor necrosis factor-α (TNF-α)." (PMID 32676164, 2020). "While, KEGG enrichment analysis indicated that they were mainly involved in the process of transcriptional dysregulation in cancer, TNF and IL-17 signaling pathways." (PMID 32704283, 2020).